CCN1 (cellular communication network factor 1)
Diseases named in the same sentence as CCN1 in open-access papers (continued):
Sharing a sentence is not in itself a finding about the gene and the disease.
cancer (194 papers, 2007 to 2026). A tumor composed of atypical neoplastic, often pleomorphic cells that invade other tissues. "Consistent with this, emerging reports have shown that CCN1 is critical for cardiovascular development during embryonic life and is associated with inflammation, wound healing, damage repair, fibrosis, and cancer in adulthood." (PMID 40225592, 2025). "Aberrant expression of CCN1 is implicated in the pathogenesis and progression of several cancer types." (PMID 41012700, 2025). "In response, the host expressed CCN1, which encodes a critical protein involved in inflammation and bacterial clearance and is linked to chronic intestinal diseases and cancer." (PMID 41278623, 2025). "Aberrant CCN1 expression is associated with various cancers, such as gastric and mammary cancers, by regulating cell adhesion, proliferation, migration, and differentiation." (PMID 35785168, 2022). "To evaluate the association between CCN1 mRNA expression and prognosis, we also examined 32 human cancers using GEPIA2." (PMID 33833779, 2021). "ECs expressing CCN1 at high stiffness increased the binding of cancer cells via N-Cadherin interactions, and CCN1 loss prevented cancer cell binding and TEM." (PMID 29209654, 2017). "CCN1 is a multifunctional protein involved in various physiological processes and its dysregulation has been implicated in pathological conditions such as aging, fibrosis, inflammation, and cancer." (PMID 41530283, 2026). "MACC1 and CCN1 are both implicated in cancer metastasis, adhesion, and survival." (PMID 38396744, 2024). "Studies have also shown that CCN1 is associated with cancer progression and invasion." (PMID 35052688, 2021). "CCN1 exhibits varying mRNA levels and associations with prognosis across different types of cancer." (PMID 33833779, 2021). "Thus, we propose that endothelial loss of CCN1 decreases cancer cell adhesion to blood vessels and reduces metastasis, likely by regulating cancer cell entry into the vasculature." (PMID 28694244, 2017). "Furthermore, intravital imaging analysis of the interaction between fluorescently labelled B16F10 cancer cells and the vasculature demonstrated that loss of endothelial CCN1 reduces cancer cell attachment to the endothelium, whilst increasing motility along the blood vessels." (PMID 29209654, 2017). "Previous studies have indicated that CCN1 can mediate resistance to antitumor therapies in various cancers through diverse mechanisms." (PMID 40234387, 2025). "CCN1 has been suggested as a potential serum biomarker for early detection of cancers with an aggressive phenotype using a liquid biopsy format." (PMID 41012700, 2025). "Notable downregulated genes included Mki67, Ccn1, Muc1, Atf3, Ntrk2, Arid5b, Igf1r, Igf2bp2, Cd47, and Cd37 (oncogenic function) and integrin-related genes, Itga7, Itga11, Itgam and Notch1 (cancer stem cell markers)." (PMID 39946195, 2025). "ECM stiffness stimulates β‐catenin nuclear translocation via the matricellular protein CCN1, which promotes the cancer cell‐endothelium interaction and thus promotes cancer cell metastasis through vasculature." (PMID 39801760, 2025). "The matricellular protein cellular communication network 1 (CCN1) is known for supporting some cancer growth but suppressing others." (PMID 39524140, 2024). "In this article, we show, for the first time in any cancer model, that CCN1 is required for both neovascularization and ECM elaboration." (PMID 38363129, 2024). "In a recent work, where we investigated the cancer/stromal cell crosstalk in a 3D cell culture model, the CCN1 gene appeared as robustly upregulated in the cancer cell Panc1 when co-cultured with pancreatic stellate cells (PSCs)." (PMID 39273316, 2024). "Recent research has shown that CCN1 is involved in the pathological processes of diseases such as fibrosis and cancer." (PMID 37887075, 2023). "Aberrantly expressed CCN1 correlates with numerous chronic inflammation-related diseases, including cancer." (PMID 35148282, 2022).
cancer (continued). "CCN1 plays an essential role in tumorigenesis and inflammatory responses in various cancers, including OC." (PMID 35785168, 2022). "The authors further examined the role of CCN1 in cancer–endothelium interactions through the co-culture of ECs and PC3 prostate cancer cells in matrices with varying stiffnesses." (PMID 35806421, 2022). "CCN1 is a secreted, heparin-binding protein which is involved in a variety of diseases, including carcinoma, bacterial clearance and inflammation." (PMID 35547732, 2022). "Some studies have confirmed that BATF2 expression is negatively correlated with CCN1 expression and regulates the biological behaviors of cancer cells via regulating CCN1 expression in vivo." (PMID 34565331, 2021). "For instance, the cell cycle regulator cellular communication network factor 1 (CCN1) plays an important role in cancer progression and inflammatory response in different solid cancers." (PMID 34503065, 2021). "By contrast, in esophageal, liver, prostate, lung, and endometrial cancer, CCN1 serves as a protective role." (PMID 33833779, 2021). "These bioinformatics results revealed the heterogeneous expression and functions of CCN1 in different types of cancer." (PMID 33833779, 2021). "The existing literature on CCN1 mainly focuses on its role in wound healing, angiogenesis, inflammation, and fibrosis, as well as on cancer research." (PMID 33105556, 2020). "Cancer patients with high CCN1 expression have poor survival outcomes and positive correlation with ITGAV and ITGB3 and high YAP/WWTR1." (PMID 31429823, 2019). "And the expression of angiogenic factors including VEGFR2 and Tie2 is significantly correlated with the expression of CCN1 in these cancer patient cohorts." (PMID 31429823, 2019). "In situ hybridization analysis revealed that Ccn1 was expressed in cancer and stromal cells, including blood vessels." (PMID 28694244, 2017). "We show that levels of endothelial CCN1 determine the binding between endothelial and cancer cells in vivo and in vitro using co‐culture assays." (PMID 28694244, 2017). "Among these, N‐cadherin/CDH2, which is notable as a cancer cell protein that promotes metastasis, was highly downregulated in response to CCN1 silencing." (PMID 28694244, 2017). "Using intravital imaging, we show that knockout of Ccn1 in endothelial cells inhibits melanoma cancer cell binding to the blood vessels, a critical step in cancer cell transit through the vasculature to metastasize." (PMID 28694244, 2017). "Here we identified another mechanism through which CCN1 plays key roles in the metastatic cascade, by mediating the crosstalk between blood vessels and cancer cells." (PMID 28694244, 2017). "Based on these considerations, we evaluated the CCN1-Prom for cancer-selective expression and identified a truncated version of this promoter (tCCN1-Prom) as a potential genomic reagent to develop conditionally replication-competent Ads." (PMID 25926554, 2015). "The CCN1/CYR61 gene displays elevated expression as a consequence of oncogenic transformation in various cancers including CaP, and expression increases with aggressiveness of the transformed cells." (PMID 25926554, 2015). "Previous studies indicated that the CCN1/CYR61 gene and its promoter are upregulated in various cancers and responsible for malignant and metastatic transformation." (PMID 25926554, 2015). "Among the various CCN proteins, a majority of studies have been conducted on Cyr61 or CCN1 with reference to cancer." (PMID 24606730, 2014). "Cysteine-rich 61 (Cyr61/CCN1), one of the members of the CCN family, is implicated in cancer invasion of human malignancies." (PMID 24216696, 2013). "Several matricellular proteins, such as SPARC, OPN, CCN1, CCN6, and TNC, have been implicated in either the promotion or suppression of EMT, highlighting their role in cancer progression and malignant behavior of cancer cells." (PMID 22481923, 2012).
cancer (continued). "Strain-induced CCN1 upregulates N-cadherin levels on the surface of ECs by promoting the nuclear translocation and signaling of β-catenin, thereby enhancing the crosstalk between cancer cells and ECs—a critical step in cancer metastasis." (PMID 40211368, 2025). "CCN1 is induced through the activation of the transcriptional co-activator YAP in cancer cells." (PMID 38396744, 2024). "CCN1 plays crucial roles in both physiological processes, like embryonic development, senescence, tissue injury repair, and angiogenesis, as well as in pathological processes such as fibrosis and cancer." (PMID 39273316, 2024). "Cellular communication network factor 1 (CCN1) is upregulated within various malignancies and associated with cancer development and progression, while the implications of CCN1 in the phenotype transition and tumorigenicity of GSCs remain unclear." (PMID 39659236, 2024). "The relationship between CCN1 expression and prognosis varied across different types of cancer." (PMID 33833779, 2021). "Thus, to resolve the discrepant roles of CCN1 in different types of cancer, future studies should take diverse TMEs and different isoforms into consideration." (PMID 33833779, 2021). "These few examples indicate towards diverse actions of CCN1 on cancer progression." (PMID 35052688, 2021). "CCN1 is known to be overexpressed in a number of different cancer types and to drive invasion." (PMID 35052688, 2021). "A study found that the expression of CCN1 in human cancer cells could be upregulated via the stabilization of G4s in the 3′-UTR of the human CCN1 mRNA near the stop codon." (PMID 35822045, 2021). "Next, we investigated whether upregulated CCN1 expression is correlated with cancer patient survival and the expression of molecules involved in tip cell activity based on data from The Cancer Genome Atlas (TCGA)." (PMID 31429823, 2019). "The genetic alterations related to CCN1 expression were investigated using a HaloPlex Cancer Research Panel, which targets Catalogue of Somatic Mutations in Cancer (COSMIC) mutations within 47 genes known to be associated with cancer." (PMID 28785028, 2017). "Hence, also in vivo endothelial Ccn1 regulates the crosstalk between cancer and endothelial cells by promoting cancer cell binding." (PMID 28694244, 2017). "Furthermore, the increase in CCN1/CCN2 expression contributes to the S1P-induced increase in cancer cell proliferation." (PMID 28460443, 2017). "In vitro data corroborated the role of endothelial CCN1 in cancer cell intravasation." (PMID 28694244, 2017). "For this reason, we addressed whether CCN1‐dependent N‐cadherin upregulation in ECs could facilitate cancer cell interactions with ECs." (PMID 28694244, 2017). "Next, we provide evidence that vascular Ccn1 controls cancer cell metastasis." (PMID 28694244, 2017). "Expression of CCN1 is significantly elevated in Hi-myc(+) mice vs. age-matched groups of normal or Hi-myc(−) mice, suggesting the potential utility of the cancer-selective tCCN1-Prom for developing oncolytic viruses with concomitant production of a therapeutic cytokine, a CTV-m7 in this model." (PMID 25926554, 2015). "In addition to angiogenesis, CCN1 can promote cancer cell proliferation, invasion, survival, and metastasis." (PMID 24606730, 2014). "We first assessed expression of CCN family members, CCN1, CCN2, CCN3 and CCN5 which have been implicated in modulating cell proliferation, cell adhesion, angiogenesis, cell migration, metastasis and epithelial-mesenchymal transition in a variety of cancers." (PMID 25541962, 2014). "CCN1-induced activation of SHh signaling may be necessary for CCN1-dependent in vitro cancer cell migration and tumorigenicity of cancer stem cells in a xenograft in nude mice." (PMID 24287901, 2013). "Furthermore, the expression level of CCN1 is highly dependent on the type and the stage of the cancer." (PMID 22701179, 2012).
cancer (continued). "In conclusion, the discovery of the involvement of Cyr61/CCN1 in pancreatic carcinogenesis may represent an important marker for PDAC and suggests Cyr61/CCN1 can be a potential cancer therapeutic target." (PMID 21232118, 2011). "However, the regulatory mechanisms of CCN1, especially how it regulates the crosstalk between cancer cells and their microenvironments in PDAC, remain largely unknown." (PMID 39273316, 2024). "In addition, bioinformatics analyses of transcriptomic datasets from Cancer Cell Line Encyclopedia database revealed significantly positive associations between USP7 expression and CYR61/CCN1 (R = 0.4498, p < 0.0111), CTGF/CCN2 (R = 0.3141, p < 0.0426) in 31 HNSCC cell lines." (PMID 35931679, 2022). "The overexpression of Cyr61 (CCN1) in the low-metastatic variant of the human SaOS-2 OS cell line increased cell proliferation and promoted lung metastasis, and both Cyr61 and CTGF (CCN2) have been implicated in the progression of bone metastases in other cancers." (PMID 31878963, 2019). "Intravital imaging analysis revealed that cancer cells can stably or transiently bind to blood vessels and, strikingly, the number of cancer cells that stably adhered to the blood vessels was significantly reduced upon depletion of Ccn1 in the endothelium (and Movies EV1 and EV2)." (PMID 28694244, 2017). "The STRN4 palmitoylation reduced YAP phosphorylation, promoted nuclear translocation of YAP and activated downstream Hippo pathway transcriptional targets—including CCN1, CCN2 and ANKRD1—thereby driving cancer cell migration." (PMID 40903842, 2025). "One protein of growing interest in cancer biology is cysteine-rich angiogenic inducer 61 (CYR61), also known as CCN1." (PMID 41009559, 2025). "VLCKD-induced nutritional ketosis promoted changes in the methylation of 18 genes (20 CpGs; 17 hypomethylated, 3 hypermethylated) belonged to cancer-related pathways with MAPK10, CCN1, CTNNA2, LAMC3 and GLI2 being the most representative genes." (PMID 40140215, 2025). "Previous studies have shown that CCN1 and CCN2 play functional roles in the development of different types of cancers." (PMID 38545253, 2024). "The stiffness-induced upregulation of N-cadherin, a protein heavily involved in cancer metastasis, was dependent on CCN family member 1 (CCN1) in a β-catenin-mediated manner." (PMID 35806421, 2022). "It is known, that the cell adhesion protein CCN1 (also known as cysteine-rich angiogenic inducer 61 or CYR61) stimulates mesenchymal migration in fibroblasts, endothelial cells, smooth muscle cells and some types of cancer cells." (PMID 35052688, 2021). "Aberrant expression of CCN1, commonly known as cysteine-rich angiogenic inducer 61 (CRY61), has been found to be related to various classes and categories of cancer." (PMID 34940056, 2021). "In cancer, the Hedgehog molecule SMO interacts directly or indirectly with several molecules, including MMPs, BMP4, Rho, CCN1, etc.." (PMID 32962123, 2020). "CCN1 and CCN2 are aberrantly expressed in many types of cancer tissues and are involved in the processes of angiogenesis and tumorigenesis." (PMID 28460443, 2017). "Here, we investigated the impact of CCN1 expression on fatty acid synthase (FASN), a metabolic oncogene thought to provide cancer cells with proliferative and survival advantages." (PMID 27713913, 2016). "Targeting YAP and/or CCN1 and CCN2 may provide clinical benefit in BCC and other cancers in which YAP is elevated." (PMID 39898007, 2025). "Consistent with the observed IAG933 activity in a subset of Hippo-unaltered cell lines, additional profiling on 263 cancer cell lines revealed higher sensitivity in cells that display high basal TEAD activity, as determined by a four-gene (CCN1, CCN2, ANKRD1 and AMOTL2) transcriptional signature." (PMID 38565920, 2024).
cancer (continued). "Given that CCN1 is a critical factor for HSV-1 resistance, we investigated the dependencies of the genes in our prioritized subnetwork using the gene dependency datasets DEMETER2 (RNAi) and Avana (CRISPR) 32,33 to further dissect GBM cancer vulnerabilities." (PMID 34045642, 2021). "CYR61/CCN1 and CTGF/CCN2 are variably deregulated in human cancers." (PMID 33670622, 2021). "The mechanism of CCN1 expression and genetic alterations in malignant tumors have not been well-characterized." (PMID 28785028, 2017). "Conversely, exogenous expression of CCN1‐GFP in ECs strongly enhanced PC3 cell adhesion and addition of an N‐cadherin‐blocking antibody completely abrogated the ability of CCN1 to promote EC–cancer cell interactions." (PMID 28694244, 2017). "Altered expressions of CCN1/CYR61, CCN2/CTGF, CCN3/NOV, and CCN4/WISP1 were found to correlate with clinical features, including venous invasion, cellular differentiation, TNM staging for malignant tumors, disease-free survival, and overall survival in HCC." (PMID 27829832, 2016). "CCN1/CYR61 is an early response gene regulated transcriptionally in a protein kinase C (PKC)- and cyclic AMP-responsive element binding protein (CREB)-dependent manner, which is often elevated in diverse cancers including CaP." (PMID 25926554, 2015). "However, CCN1 silencing using a doxycycline-inducible shRNA system 24 h after cancer cell injection did not influence the lung metastasis." (PMID 33105556, 2020).